SIRT3 (sirtuin 3)
Diseases named in the same sentence as SIRT3 in open-access papers (continued):
Sharing a sentence is not in itself a finding about the gene and the disease.
epilepsy (5 papers, 2022 to 2025). A brain disorder characterized by episodes of abnormally increased neuronal discharge resulting in transient episodes of sensory or motor neurological dysfunction, or psychic dysfunction. "Subsequently, we performed a stratified analysis based on the NHS3 and MOCA scores of all epilepsy patients to evaluate the association between SIRT3 and the severity of the patients." (PMID 39091611, 2024). "In this study, we found that serum SIRT3 levels were significantly decreased in epilepsy patients and were a risk factor for refractory epilepsy." (PMID 39091611, 2024). "Therefore, in this prospective observational study, we aimed to investigate the serum levels of SIRT3 in epilepsy patients and its association with the severity of the disease." (PMID 39091611, 2024). "Furthermore, understanding the underlying mechanisms by which SIRT3 influences epilepsy holds significant promise for the development of novel treatment approaches." (PMID 39091611, 2024). "Furthermore, we evaluated the diagnostic value of serum SIRT3 levels in epilepsy patients using ROC curve analysis." (PMID 39091611, 2024). "Moreover, we found an association between SIRT3 and cognitive function in epilepsy patients." (PMID 39091611, 2024). "A prospective observational study reported that SIRT3 levels were significantly decreased in epilepsy patients, and even lower in drug-resistant epilepsy cases." (PMID 40969935, 2025). "Our findings also demonstrated that serum SIRT3 levels were negatively correlated with inflammatory factors IL-6 in epilepsy patients." (PMID 39091611, 2024). "In conclusion, our findings demonstrated that serum SIRT3 levels were significantly decreased in epilepsy patients and further decreased in patients with refractory epilepsy." (PMID 39091611, 2024). "Only one animal study has focused on the mechanism of SIRT3 in epilepsy, which showed that activating SIRT3 can alleviate hippocampal pathological damage, promote mitochondrial autophagy, and reduce oxidative stress in epilepsy rats." (PMID 39091611, 2024). "Subsequently, we assessed the correlations between serum SIRT3 levels and the inflammatory factor levels, as well as the clinical characteristics of the epilepsy patients using Pearson’s correlation analysis." (PMID 39091611, 2024). "Lastly, further in-depth research is needed to elucidate the molecular mechanisms by which SIRT3 is involved in the development of epilepsy." (PMID 39091611, 2024). "In conclusion, our findings demonstrated that serum SIRT3 levels were decreased significantly in epilepsy patients and further decreased in patients with refractory epilepsy." (PMID 39091611, 2024). "Additionally, SIRT3 regulated astrocyte activation via the Notch1/NF-κB pathway, which helps alleviate the inflammatory response after epilepsy." (PMID 40969935, 2025). "It is worth noting that SIRT3 could enhance autophagy by regulating the AMPK/mTOR pathway to exert a protective effect against epilepsy induced brain damage." (PMID 40969935, 2025). "Additionally, we found that SIRT3 can be used for diagnosing epilepsy and distinguishing patients with refractory epilepsy." (PMID 39091611, 2024). "Furthermore, activation of SIRT3 has been shown to alleviate pathological damage in the hippocampus of epilepsy rat models, promote mitochondrial autophagy, and reduce oxidative stress." (PMID 39091611, 2024). "Factors such as age, gender, comorbidities, medication history, and lifestyle factors may have an impact on SIRT3 levels and epilepsy outcome." (PMID 39091611, 2024). "Another limitation is the lack of detailed assessment of potential confounding factors that could influence the relationship between SIRT3 and epilepsy." (PMID 39091611, 2024). "The ROC curve demonstrated that serum SIRT3 could be used to diagnose epilepsy, with an area under the curve (AUC) of 0.845, a cutoff value of 208.82 pg/mL, a sensitivity of 83.1%, and a specificity of 65.5%." (PMID 39091611, 2024).
epilepsy (continued). "Moreover, all epilepsy patients were divided into two groups based on the average serum SIRT3 level of 195.02 pg/mL: the low SIRT3 group (n = 100) and the high SIRT3 group (n = 103)." (PMID 39091611, 2024). "SIRT3’s involvement in mitochondrial function, oxidative stress, and neuroinflammation suggests that modulating its activity or expression could represent a potential therapeutic target for epilepsy." (PMID 39091611, 2024). "Furthermore, the receiver operating characteristic curve demonstrated that serum SIRT3 could be used to diagnose epilepsy, as well as refractory epilepsy." (PMID 39091611, 2024). "Compared to the healthy volunteers, epilepsy patients had significantly increased serum levels of the inflammatory factors IL-6, IL-1β, TNF-α, and CRP (P < 0.05), while SIRT3 levels were significantly decreased." (PMID 39091611, 2024). "Epilepsy patients with lower NHS3 scores had significantly higher levels of SIRT3, while those with lower MOCA scores had significantly lower levels of SIRT3 (P < 0.05)." (PMID 39091611, 2024). "Furthermore, it is plausible that the extent of SIRT3 depletion, as well as the specific molecular pathways affected by SIRT3 dysregulation, may vary among different epilepsy subtypes, which may lead to possible limitations in the generalizability of our findings." (PMID 39091611, 2024). "Therefore, we further investigated the levels of serum biomarkers, including SIRT3, IL-6, IL-1β, TNF-α, and CRP in epilepsy patients." (PMID 39091611, 2024). "Additionally, we found that SIRT3 levels were negatively correlated with the NHS scores (Pearson’s correlation −0.272, P < 0.001) of epilepsy patients, while positively correlated with MOCA scores (Pearson’s correlation 0.166, P = 0.018)." (PMID 39091611, 2024). "In a rat model of pentylenetetrazole (PTZ)-induced epilepsy, we quantify 43 acylations in 29 cerebral cortex proteins; levels of NAD+; expression of NAD+-dependent deacylases (SIRT2, SIRT3, SIRT5); activities of the acyl-CoA-producing/NAD+-utilizing complexes of 2-oxoacid dehydrogenases." (PMID 36293175, 2022). "However, there is currently a lack of research on the expression of SIRT3 in epilepsy patients and its clinical implications, particularly in relation to the severity of the disease." (PMID 39091611, 2024). "In addition, serum SIRT3 levels were negatively correlated with the inflammatory factors IL-6 (Pearson’s correlation −0.221, P = 0.002) and NHS score (Pearson’s correlation −0.272, P < 0.001) of epilepsy patients, while positively correlated with MOCA scores (Pearson’s correlation 0.166, P = 0.018)." (PMID 39091611, 2024).
hearing loss (5 papers, 2014 to 2021). "In summary, our results revealed that HFD consumption-mediated downregulated expression of SIRT1 and SIRT3 and aging together lead to hearing loss." (PMID 33889076, 2021). "Previous studies reported that activation of Sirt3 by the NAD+ precursor nicotinamide riboside (NR) protects from noise-induced hearing loss." (PMID 30445987, 2018). "Additionally, MNAM-mediated cochlear upregulation of SIRT1 and SIRT3 protein expression levels exerted a preventive effect against the HFD- and aging-induced hearing loss." (PMID 33889076, 2021).
hypertensive nephropathy (5 papers, 2017 to 2025). Kidney damage that results from chronically elevated blood pressure; complications include glomerular damage resulting in proteinuria and hematuria. "Catalase has been described as a critical player in SIRT3-Foxo3a-mediated EndMT in hypertensive renal disease." (PMID 34458332, 2021). "In this study, we studied the function and molecular mechanism of SIRT3 in hypertensive nephropathy." (PMID 28465484, 2017). "Taken together, our findings showed that SIRT3-KO mice developed aggravated hypertensive nephropathy and deteriorated renal function, indicating that SIRT3 may be involved in the signaling pathways mediating hypertensive kidney injury." (PMID 28465484, 2017). "Therefore, we were aimed to explore the role and possible molecular mechanism of SIRT3 in hypertensive nephropathy." (PMID 28465484, 2017). "In our study, we would explore whether HKL alleviate renal damage via elevating the expression of SIRT3 and activating its targets in hypertensive nephropathy." (PMID 28465484, 2017). "However, the function and possible molecular mechanism of SIRT3 in hypertensive nephropathy remains unclear." (PMID 28465484, 2017). "It is suggested that SIRT3 may prevent podocyte damage in hypertensive nephropathy." (PMID 28465484, 2017). "Sirtuins, particularly SIRT3 and SIRT6, have been shown to exert protective effects in the pathogenesis of hypertensive nephropathy through various biological functions such as antioxidative stress, anti-apoptosis, anti-fibrosis, anti-inflammation, and anti-mitochondrial injury." (PMID 40218970, 2025). "Whether SIRT3 could directly regulate and deacetylate KLF15 in hypertensive nephropathy requires further studies." (PMID 28465484, 2017). "In conclusion, for the first time, our findings demonstrate that SIRT3 plays a renoprotective role by deacetylating KLF15 and the SIRT3-KLF15 signaling may be a novel pathway to contribute to prevent hypertensive nephropathy." (PMID 28465484, 2017). "The effect of SIRT3, a member of the NAD+-dependent deacetylase family, in hypertensive nephropathy remains unclear." (PMID 28465484, 2017). "Furthermore, SIRT3 is prominently expressed in renal cortical tubular cells from younger mice and gradually decreases over time, as well as with AKI, DN, and hypertension nephropathy." (PMID 34518519, 2021).
liver disease (5 papers, 2016 to 2025). "The findings suggest that these agents, as SIRT3 modulators, could potentially be used in treating oxidation-injury hepatocytes and liver diseases as well as liver toxicity caused by side effects of therapeutic medications." (PMID 39859490, 2025). "SIRT3 could be a potential target in the management of hepatic diseases." (PMID 29072685, 2017).
lymphoma (5 papers, 2019 to 2022). A malignant (clonal) proliferation of B- lymphocytes or T- lymphocytes which involves the lymph nodes, bone marrow and/or extranodal sites. "Subsequently, we directly investigated if lymphoma growth related to ATM deficiency is a result of SIRT3 stimulation." (PMID 33273545, 2020). "Targeting SIRT3 dependent metabolic control of tumor cells in ATM deficient lymphoma patients will have clinical significance and likely lead to alternative novel therapeutic strategies in these patients." (PMID 33273545, 2020). "Although NAD+ supplementation in A-T models is helpful in overcoming A-T neuropathology by improving NAD+/SIRT1 axis, we suspect NAD+ will fuel tumor proliferation in A-T lymphoma cases associated with increased SIRT3 expression." (PMID 33273545, 2020). "In summary, we show that enhanced SIRT3 expression promotes lymphoma growth in an ATM deficient background." (PMID 33273545, 2020). "This is the first study directly demonstrating that SIRT3 is critical metabolic target associated with lymphoma development in ATM−/− background." (PMID 33273545, 2020). "Hence, ATF4 is aberrantly expressed in primary murine and human lymphomas, where it appears to be linked to SIRT3 expression and inversely correlated with autophagy." (PMID 35019856, 2022). "We also examined the degree of autophagy in these tumors by determining their LC3II and LC3I ratios by Western blot analysis, which confirmed higher levels of autophagy in Sirt3−/− lymphomas." (PMID 35019856, 2022). "Using Western blots, we showed that indeed ATF4 protein levels were significantly decreased in VavP-Bcl2;Sirt3−/− versus VavPBcl2;Sirt3WT primary lymphomas." (PMID 35019856, 2022). "Our data illustrates the clinical significance of targeting addiction to SIRT3 influenced metabolic pathways in order to impede lymphoma growth in presence of low ATM expression." (PMID 33273545, 2020). "Staining of ATM, SIRT1 and SIRT3 in lymphoma patients demonstrated a variation in their degree of expression suggesting a differential requirement of these critical markers during tumor development." (PMID 33273545, 2020). "We discovered the link between SIRT3 and ATF4 in DLBCL cells, which connected lymphoma amino acid metabolism with ATF4 translation via metabolic stress signals." (PMID 35019856, 2022). "To validate the reporter in our lymphoma system, we performed Western blots in DLBCL cells expressing the ATF4-5′UTR-GFP after induction of SIRT3 or control shRNA." (PMID 35019856, 2022). "To determine if SIRT3 assists DLBCL cells to resists metabolic stress, we first determined expression of SIRT1, SIRT3 and ATM in human lymphoma samples to understand clinical relevance of these markers in DLBCL." (PMID 33273545, 2020). "Only SIRT3 and SIRT7 were downregulated in lymphoma, AML and CML." (PMID 36230534, 2022). "Given our data showing that SIRT3 is required to maintain ATF4 expression in DLBCL cell lines, we next examined whether this was also the case in primary lymphomas developing in vivo." (PMID 35019856, 2022). "Finally, although ATF4 protein showed positive correlation with the relative abundance of phospho-EIF2A (p-EIF2A/EIF2A), the phospho-EIF2A levels only showed the trend of decrease in Sirt3−/− versus Sirt3WT lymphomas cells but was not statistically significant." (PMID 35019856, 2022).
memory impairment (5 papers, 2019 to 2024). "Pine nut antioxidant peptides have been demonstrated to ameliorate the memory impairment of mice via regulating Sirt3-induced synaptic plasticity." (PMID 38613012, 2024). "In summary, we have shown that ketones protect ApoE4 related learning and memory impairment via Sirt3 regulation." (PMID 31280254, 2019). "Results showed that I/S induced hippocampus-dependent learning and memory impairments, with increased ROS levels, and reduced OCR, MMP, and expression and deacetylation activity of Sirt3 in hippocampus tissues." (PMID 31652451, 2019).
polycystic ovary syndrome (5 papers, 2023 to 2025). A disorder that manifests as multiple cysts on the ovaries. "The importance of SIRT3 in granulosa and cumulus cells is further highlighted by the fact that its dysregulation has been associated with various reproductive disorders, such as polycystic ovarian syndrome and age-related infertility." (PMID 39329773, 2024). "SIRT3 plays a key role in oocyte maturation and alleviates polycystic ovary syndrome by modulating the FOXO1/PGC-1α+β signaling pathway." (PMID 39595642, 2024). "In the reproductive system, metformin can improve polycystic ovary syndrome by upregulating the expression level of SIRT3 and activating the SIRT3/AMPK/mTOR pathway to inhibit ferroptosis." (PMID 37153222, 2023). "Previous studies have demonstrated that metformin can increase the expression of SIRT3 and GPX4, significantly elevate the levels of p-mTOR and p-AMPK, and improve polycystic ovary syndrome in mice by inhibiting ovarian ferroptosis." (PMID 41480421, 2025).
Ureteral obstruction (5 papers, 2020 to 2024). Obstruction of the flow of urine through the ureter. "Quan Y., Park W., Jin J., Kim W., Park S.K., Kang K.P. Sirtuin 3 activationby honokiol decreases unilateral ureteral obstruction-inducedrenal inflammation and fibrosis via regulation of mitochondrial dynamicsand the renal NF-κB-TGF-β1/Smad signaling pathway." (PMID 38680178, 2024). "Moreover, SIRT3 activation has been reported to have protective effects against renal tubulointerstitial fibrosis induced by unilateral ureteral obstruction through the NF-κB/transforming growth factor-β1/Smad signaling pathway." (PMID 37275851, 2023). "In the unilateral ureteral obstruction (UUO) mouse model, decreased SIRT3 levels and increased acetylation in mitochondria have been detected." (PMID 37196115, 2023). "Thus,honokiol – a SIRT3 activator – counteracts kidney fibrosis inmice with unilateral ureteral obstruction.Similarly, activation of both SIRT1 and SIRT3 by resveratrolattenuates cardiac fibrosis in mice by inhibiting the TGF-β/Smad3 pathway." (PMID 38680178, 2024).
age (4 papers, 2014 to 2023). A temporal measurement of the time period elapsed since an identifiable point in the life cycle of an organism. "On the other hand, SIRT3 plays a functional role in age-related periodontal diseases and their underlying mechanisms." (PMID 35630070, 2022). "Generally, valuable complementary findings were acquired in this study that the AMPK/SIRT3/SOD2 signaling pathway implicated inhibits the generation of ROS and mtROS in the case of age-related TJ function disorder in SCs." (PMID 36846717, 2023). "Another group recently showed that Sirt3−/− mice developed age-related cardiac dysfunction likely due to increased acetylation of various mitochondrial energy producing proteins resulting in myocardial energy depletion." (PMID 26370974, 2015).
amyloid (4 papers, 2021 to 2023). "Therefore, we generated APP/PS1/Sirt3-/- mouse as a model for comorbid AD with amyloid pathology and MetS." (PMID 36396721, 2022). "SIRT3 activation in vivo also increased the levels of neprilysin, another Aβ degrading enzyme and decreased the levels of BACE1 which generates Aβ peptide suggesting SIRT3’s role in amyloid plaque reduction." (PMID 36396721, 2022).
breast tumor (4 papers, 2016 to 2024). "Reduction of Sirt3 expression occurs in human breast tumors, and its loss correlates with the activation of HIF1 target genes." (PMID 35938164, 2022). "SIRT3 is deleted in 40% of human breast tumours, and loss of SIRT3 increases reactive oxygen species production and HIF-1a stabilization." (PMID 27923043, 2016). "Thus, Sirt3 knockout mice may spontaneously develop breast tumors." (PMID 35938164, 2022).
colitis (4 papers, 2016 to 2026). Inflammation of the colon. "DNBS-colitis drove myenteric neurodegeneration to a similar extent in Sirt3−/− animals as wt mice (31% neuron loss in wt vs. 25% neuron loss in Sirt3−/−)." (PMID 27047337, 2016). "DNBS drove colitis to an equal extent in both wt and Sirt3−/− mice." (PMID 27047337, 2016). "Likewise, the ablation of Sirt3 does not affect the susceptibility of enteric neurons to degeneration during colitis or their redox state." (PMID 27047337, 2016). "Loss of Sirt3 did not affect the extent of macroscopic tissue damage nor did it significantly change the pattern of weight loss experienced by the mice during the acute episode of colitis." (PMID 27047337, 2016). "The mRNA levels of Sirt1 and Sirt3 were not significantly changed in each tissue after colitis induction." (PMID 38415949, 2024). "Contrary to our data, a study showed that a mice model of inflammation (DNBS-colitis) with SIRT3 deletion as well as SIRT3 inhibition did not increase oxidative damage in their myenteric neurons when compared to the wildtype mice." (PMID 36543902, 2022). "We did not detect any obvious changes in Sirt3 expression or localization within the myenteric plexus during DNBS colitis in wt mice." (PMID 27047337, 2016). "The results above suggest that Sirt3 is not an essential protective factor against the gross inflammatory insult driven by DNBS colitis in mice." (PMID 27047337, 2016).
COVID-19 (4 papers, 2022 to 2024). A disease caused by infection with severe acute respiratory syndrome coronavirus 2. "In COVID-19, severely ill patients have significantly lower levels of SIRT3, and its levels are negatively correlated with CRP and procalcitonin levels, indicating the association of serum SIRT3 levels with clinical outcomes and prognosis in COVID-19 patients." (PMID 39091611, 2024).